TLR4 (toll like receptor 4)
Diseases named in the same sentence as TLR4 in open-access papers (continued):
Sharing a sentence is not in itself a finding about the gene and the disease.
infection (continued). "Notably, SPexp mice had increased frequencies of TLR2+ and TLR4+ leukocytes, consistent with observations in microbially experienced laboratory mice CoH with pet store mice, cumulatively demonstrating that sequential infection alters the activation status of multiple cell types." (PMID 35878936, 2022). "In vivo studies with L. chagasi suggested infection-mediated upregulation of TLR-2 and TLR-4 along with increased expression of IL-17, TNF-α, and IFN-γ during early hours of infection." (PMID 35531875, 2022). "Here, we show that both TLR4 and TLR2 act in conjunction in macrophages to promote IFN-β gene expression upon infection, and that this is entirely dependent on PKR." (PMID 35154115, 2022). "Leukocytes expressed TLR2, TLR3, TLR4, TLR6, and TLR7 can interact with RSV and promote immune responses following infection." (PMID 35308390, 2022). "Studies with CD14-deficient mice, however, demonstrated that, in the presence of high levels of LPS, as it occurs in an acute and rapid infection, the contribution of CD14 in promoting the binding of LPS to TLR4 is negligible." (PMID 36142813, 2022). "To evaluate whether SLAMF8 can modulate the expression of TLR4 and SLAMF9 and, therefore, influence the observed phenotype in SLAMF8-deficient mice, we analyzed their expression in pMø by RT-PCR after treatment with IFNγ (100 U/ml for 16 h) and infection with S. typhimurium at different time points." (PMID 35837407, 2022). "Studies have reported the role of RAGE in HMGB1‐induced inflammation, regeneration and autophagy and reported that TLR4 recognizes several danger signals, including HMGB1, to activate the innate immune system to prevent infection and injury." (PMID 34953035, 2022). "Upon infection, the activation of TLR2 and TLR4- mediated signaling pathways leads to lysosomal degradation of the bacteria." (PMID 36619761, 2022). "The first wave is mediated by the activation of TLR4 between 4 and 6h after infection followed by the second mucolipin transient receptor potential 3 (TRPML3)-activated wave occurring around 8h after infection." (PMID 36081496, 2022). "TLR4 knockout and NGAL knockout mice had significantly higher lung bacterial loads at 12 hours post infection, which was reduced significantly by exogenous NGAL administration 4 hours prior to sacrifice." (PMID 35273609, 2022). "Two homologous Brucella proteins (BtpA/TcpB and BtpB), translocated into host cells during infection, have been described to interfere with TLR2 and TLR4 signalling by inducing ubiquitination and degradation of the MAL/TIRAP adaptor molecule." (PMID 35888979, 2022). "We observed that leptospires triggered the production of ROS 6 h post-infection and that it was dependent on TLR2/TLR4." (PMID 35899053, 2022). "After 24 h of infection, the TLR2 and TLR4 mRNA expression levels were significantly decreased in the coaggregation group compared with the coinfection group (***p <0.001)." (PMID 35573793, 2022). "Signalling mediated by TLR4 activates the synthesis of ITGAM/CD11b, which is essential for the migration and adhesion of polymorphonuclear leukocytes to infection sites." (PMID 35264251, 2022). "While 100% of rASP-1-adjuvanted IIV3 immunized WT mice survived the H1N1 i.n. viral challenge (7500TCID50), the TLR4-/-, TRIF-/-, and IFNAR-/- immunized mice succumbed to the infection." (PMID 36119026, 2022). "Across in ovo treatment, the expressions of IL-2, IL-6, IL-10, TGF-β4, TLR-4, 1α-hydroxylase, and VDR were significantly higher at 2 wk post-infection (28 doa) in comparison to their expression levels before coccidiosis infection (14 doa)." (PMID 36230268, 2022). "In conclusion, we have established a connection between TLR4-NE, PKR activation, and gene expression of IFNs-I, IL10, SOD-1, and OASL2 upon infection of murine macrophages by L. donovani." (PMID 35154115, 2022).
infection (continued). "The process is induced by a variety of cell activation signals, including the stimulation of inflammation or infection of the tumor necrosis factor receptor (TNFR) and the stimulation of the Toll-like receptor 4 (TLR4)." (PMID 35566778, 2022). "B. pseudomallei can be recognised by both TLR4 and TLR2, and this has been demonstrated in vitro, but in vivo TLR2 is responsible for the detection of LPS and host response to infection." (PMID 36271712, 2022). "After activation of TLR4, a pro-inflammatory response consisting of IL8, IL17, and MIP1β is triggered resulting in the recruitment of inflammatory cells to the site of infection." (PMID 36365008, 2022). "To verify the intervention effect of VSP on TLRs, we examined the expression of TLR4 and TLR5 in 5637 (HTB-9) bladder epithelial cells after infection with UPEC." (PMID 36506014, 2022). "TrpRS is secreted into the extracellular milieu by monocytes upon infection with certain pathogens and it interacts with TLR2 and TLR4 leading to the secretion of TNFα, neutrophil infiltration, and increased phagocytotic abilities." (PMID 35634293, 2022). "Other than their latent role until the presence of infection, it is noteworthy to investigate the potential functions of TLR3 and TLR4 during development in the future." (PMID 34395439, 2021). "Several TLRs have been described as important molecules in the resistance to T. cruzi experimental infection, such as TLR2, TLR4, TLR7, and TLR9." (PMID 34336720, 2021). "Thus, it is not surprising that polymorphisms in TLR4 might cause predisposition to susceptible infection by S. Typhi." (PMID 33562108, 2021). "During the course of infection by FMDV, VP3 interacts with Rab7b and TLR4 and subsequently attenuates the expression of Rab7b, which results in the upregulation of TLR4 expression." (PMID 34524915, 2021). "Human peripheral monocytes from L. braziliensis-infected patients with CL exhibited higher expression of TLR2, TLR4, TNF-α and IL-10 upon infection in vitro with L. braziliensis." (PMID 33924130, 2021). "The mRNA expression levels of TLR4–7 and TLR10 were significantly higher in KoRV-B-and KoRV-C-positive koalas than in those with endogenous infection only (KoRV-A; KJ, KY, and KYB)." (PMID 33915914, 2021). "Other immune regulatory molecules, such as CD14 and CSF2, were significantly up‐regulated, while others, such as TLR4, IRF9 and CD36, were significantly down‐regulated after infection with H37Rv." (PMID 34632719, 2021). "This study found that the expression of TLR4 and TLR7 increased obviously after infection, and the percentage of TLR7 expressing B cells was higher than that for TLR4 expressing B cells in the infected mice." (PMID 34788282, 2021). "Conversely, very strong colocalization of TLR4 and VP1 at low virus input (MOI = 1) was observed 4 days post-infection (4 dpi), as quantified using Pearson′s correlation coefficient (PCC) by including pixels that co-localize between both channels." (PMID 33923020, 2021). "As one of the Toll-like receptors (TLRs), Toll-like receptor 4 (TLR4) plays a key role in recognizing and resisting the infection of bacteria in ducks." (PMID 34944363, 2021). "The expression of IL-1β, IL-6, IL-8, IL-18, TNF-α, MMP-9, RANKL, TLR-2, TLR-4, TLR-6, thymic stromal lymphopoietin (TSLP), and ICAM-1 was evaluated by qPCR at 2 and 24 h after infection." (PMID 33802988, 2021). "Our previous work has shown that monocytes from CL patients express ex vivo and after infection with L.braziliensis more TLR2 and TLR4 than monocytes obtained from healthy individuals; again, this was linked to TNF expression." (PMID 34691019, 2021). "As the full extent of the immune response likely involved independent as well as synergistic effects, we employed both TLR4 and TLR2 to stimulate immune cells from the blood and to artificially recreate a multiorganism infection." (PMID 34439987, 2021).
infection (continued). "Infection by SARS-CoV-2 induces the release of a proinflammatory cytokine such as IL-1β through activation of TLR2 (toll-like receptor 2), TLR3, or TLR4." (PMID 34306796, 2021). "In regulating microbe-elicited ROS production during an antimicrobial response, many studies showed that host PRRs (mainly TLR2, TLR4, NOD2, NLRX1, and NLRP3) and redox modulation alleviated pathogen infection." (PMID 34299310, 2021). "The mRNA levels of TLR4 in Mφ, HCT116, and SW480 cells were obviously increased in response to Fn infection." (PMID 34093546, 2021). "We recorded a significant upregulation in expression of TLR4 and TLR21 in S. Typhimurium-infected chMoDCs in comparison with that in the S. Gallinarum group during the early phase of infection (6 h)." (PMID 34446765, 2021). "In alignment with the TLR4 trends, LPS-inducible PIGR was also upregulated only during the ground infection." (PMID 33750813, 2021). "Because the magnitude of the effect of the gene KO was comparable across these four TLRs, we posit that TLR2, TLR3, TLR4, and TLR5 are equally important in the macrophage response to L. pneumophila at least at the early stages of infection." (PMID 34280250, 2021). "TLR9 and FoxP3 were up-regulated in dog skin at the early stages of infection and in lymph nodes and significant downregulation of TLR3, TLR4, TLR9, IL-17, IL-22, and FoxP3 transcription was found associated with disease progression." (PMID 33352885, 2020). "In this model of infection, ALI would induce DAMP release from damaged tissues, likely HMGB1 and oxidized phospholipids, which, in turn, hyperactivate TLR4 with a subsequent cytokine storm and acute sepsis-like syndrome." (PMID 32765484, 2020). "We generate 977 miRNA-sequencing profiles from primary monocytes from individuals of African and European ancestry following activation of three TLR pathways (TLR4, TLR1/2, and TLR7/8) or infection with influenza A virus." (PMID 32731901, 2020). "In this context, HMGN1 was shown to act as an alarmin by inducing maturation in human dendric cells via Toll-like receptor 4 (TLR-4) and by recruiting antigen-presenting cells (APCs) to the site of infection." (PMID 31936777, 2020). "These animals also had higher fungal loads during infection with F. pedrosoi conidia, confirming that TLR-2 and TLR-4 are essential receptors for F. pedrosoi recognition and immune system activation." (PMID 33193308, 2020). "Infection of the cells with M. haemolytica increased both TLR protein levels, whereas LPS stimulation only resulted in a significant increase in TLR4 protein levels." (PMID 32747652, 2020). "The TLR4 expression in the immunocompetent Acanthamoeba spp.-infected mice was similar to TLR2 expression and remained at a similar level during the infection." (PMID 32958053, 2020). "Gal-3 is also a known agonist of toll like receptor 4 (TLR4) and nuclear factor kappa beta (NF-kB) dependent pathways, which are well characterized and potent inducers of inflammation during infection (Yipet al., 2017;Zhouet al., 2018)." (PMID 33082935, 2020). "We demonstrate that phagocytosis and reactive oxygen species during infection with conidia are TLR-2– and TLR-4–dependent and are essential for conidial killing." (PMID 33193308, 2020). "In response to TLR1/2 (PamCys2) or TLR4 (LPS) stimulation, monocytes produced a strong TNF and moderate IL‐12 response, which increased at peak infection." (PMID 32566226, 2020). "Confirming the Irf1 transcription data, L. infantum-mCherry infection induced IRF1 expression in the WT BMDCs, whereas the Tlr4-/- BMDCs displayed significant reduction in protein expression (average of 50% reduction)." (PMID 32210480, 2020). "The quantification of the most prominent intestinal bacterial genera by molecular microbiota analyses revealed that, until the day of the first infection, the human gut microbiota had established in both IL10-/- and TLR4-/- IL10-/- mice." (PMID 32443576, 2020).
infection (continued). "The levels of MDA and UCP2 were significantly increased due to the infection of S. uberis in WT, TLR2−/−, and TLR4−/− mice (p < 0.05)." (PMID 32098158, 2020). "On the other hand, the pyrimidoindole derivative 1Z105 was found to activate TLR4 in a MyD88-biased fashion, leading to a TH2 response, which is better in fighting parasites and extracellular pathogens infections." (PMID 32765484, 2020). "In the current study, following infection of rohu with A. invadans, TLR2, TLR3, TLR4 and TLR9 were downregulated." (PMID 33177569, 2020). "The level of IL-10 expression was similar in that in MAH/LPS-infection and LPS-treatment of TLR2−/− DCs and in MAH/LPS-infection and MAH-infection of TLR4−/− DCs, whereas IL-10 production was strongly increased in MAH/LPS-infection in WT DCs." (PMID 31440223, 2019). "We observed upregulation of TLR2, TLR4, and downregulation of TLR10 at the chronic stages of infection." (PMID 31555289, 2019). "To answer this question, we infected wild type or Tlr4-/- mice with chronic LCMV, and at day 45 post-infection, mice received PD-L1 blocking antibodies." (PMID 30726291, 2019). "In comparison to the control uninfected group, mRNA expression levels of TLR3, TLR4, TLR7, MyD88, RIG-1 and NF-κB p65 in the control infected group were prominently increased on days 3 and 7 post-infection (all P < 0.01)." (PMID 31551774, 2019). "Lastly, intestinal TLR4 mRNA upregulation and HMGB1 protein levels were increased in both TLR4 and HMGB1 proteins in the pig ileal tissue 120 hrs after the infection with Clostridium perfringens type C." (PMID 31847111, 2019). "Although treatment of mice with the TLR4-specific inhibitor Eritoran blunts IFN-β gene and protein expression in influenza virus-infected mice, the mice survive an otherwise lethal infection." (PMID 31064834, 2019). "Infection with S. Typhimurium and S. Dublin led to a significant downregulation of TLR2, TLR3, TLR4, TLR5, and TLR7 in chicken macrophages HD11, whereas only a slight downregulation of TLR3 and TLR7 genes was observed in the S. Gallinarum infection group." (PMID 31998655, 2019). "The lipid A pattern is recognized by the TLR4/MD2 complex, leading to the activation of innate signaling pathways and resulting in inflammation and clearance of the infection." (PMID 30745327, 2019). "First, we showed that after infection with L. braziliensis there is an increase in TNF expression and it occurs predominantly in TLR2 (+) and TLR4 (+) cells." (PMID 31119102, 2019). "We also demonstrate that following in vitro infection with L. braziliensis, TLR2 and TLR4 expression is up-regulated in cells from CL patient monocytes as compared to HS monocytes." (PMID 31119102, 2019). "Seven days post-infection, the EP birds had remarkably higher expression levels of NF-κB, PPAR-γ, TLR4, and IL-1β (P < 0.05)." (PMID 29948799, 2019). "Our results reveal that infection with L. braziliensis increases the expression of TLR2 and TLR4 on inflammatory monocyte subsets and this increase is accomplished mainly by TNF production." (PMID 31119102, 2019). "First, we show that activation of major innate immunity pathways, such as TLR1/2, TLR4 and TLR7/8, and infection with a live strain of IAV increase isoform diversity and elicit a marked remodelling of the isoform repertoire." (PMID 30975994, 2019). "Whereas the protein levels of TLR3 and TLR4 declined at 12 h and 24 h, respectively, after infection by wild-type HCMV, they were barely affected by infection with HCMVΔUS7-16." (PMID 31604943, 2019). "In fact, the infection with L. braziliensis increased the expression of TLR2 and TLR4 on intermediate monocytes." (PMID 31119102, 2019). "Activation of TLR4, IL15R, IL1R1, and IL1A is important for antimicrobial activity, a key function for infection control." (PMID 29593724, 2018).
infection (continued). "This process is catalyzed by enzymes of the phospholipase A2 (PLA2) superfamily and is induced by various cellular activation signals, including inflammation or infection driven tumor necrosis factor receptor (TNFR) and toll-like receptor 4 (TLR4) stimulation." (PMID 30360467, 2018). "In contrast to the liver tissue, significant upregulation of TLR3, TLR4, and TLR10, but downregulation of TLR7, characterized hepatocytes derived from livers of animals with resolved AH accompanied by secondary occult infection." (PMID 30581424, 2018). "With TLR4 inhibitor pretreatment, ATF4 protein levels in infected mouse corneas at 1 day after infection and HCECs at 16 hours after A. fumigatus infection were significantly suppressed (P < 0.05, respectively)." (PMID 30647960, 2018). "Phosphatidylinositol-4,5-bisphosphate 3-kinase (PI3K), a cell survival factor that prevents premature apoptotic cell death, is activated during infection with IAV, RSV, DENV, and SARS-CoV, and PI3K activation can be mediated by TLR4." (PMID 30571771, 2018). "HSPCs express Toll-like receptors (TLR), such as TLR4 and TLR2, enabling them to recognize and respond to infection." (PMID 29898768, 2018). "Extracellular and endocytosed LPS is recognized by the transmembrane protein Toll-like receptor 4 (TLR4), leading to gene transcriptional regulation in response to infection." (PMID 30138458, 2018). "In comparison with wild-type bacteria, infection with the complemented PA14 ΔflgK pUCP19-flgK and PA14 ΔpopB pUCP19-popB strains restored to varying degrees the protein levels of TLR4, TLR5, NLRC4, caspase-4 and mature IL-1β and IL-18." (PMID 28469996, 2017). "Upon infection with Leptospira sp., iNOS is expressed 3 days post-infection in kidneys and lungs of mice in a TLR2- and TLR4-dependent manner." (PMID 28270811, 2017). "Shortly after de novo infection, KSHV activates both the host TLR4 signaling pathway and expression of HO-1, and then the CO generated as a result of KSHV-induced HO-1 activity downmodulates TLR4 signaling and promotes KSHV infection." (PMID 28421060, 2017). "The Toll-like receptor 4 (TLR4) pathway involves in the pathogen recognition and defense against infection in mammals." (PMID 28464901, 2017). "Other studies have shown that KSHV binding to endothelial cells results in rapid activation of the TLR4 pathway, and induction of NRF-2, the latter mechanism being essential for establishment of de novo infection." (PMID 28421060, 2017). "CSFV Shimen infection results in a significant induction of TLR2, TLR4, and TLR7, but decreased of TLR3." (PMID 28751780, 2017). "In this study, we found a significant and consistent increase in TLR2, TLR4, and TLR9 transcripts in the brains of lethally infected mice at days 6 and 10, as well as in brains of sublethal infection." (PMID 28742087, 2017). "Several classes of TLRs, including TLR4, TLR7, TLR8, and TLR9, are expressed on human CD34+ cells, suggesting that HSCs have an early mechanism to immediately detect infection." (PMID 29181334, 2017). "To investigate the effects of CCM111 on infection-mediated signaling, we further investigated the effects of CCM111 on the TLR2, TLR3 and TLR4 signaling pathways using stable cells and luciferase reporter assays." (PMID 28687744, 2017). "Changes in mesothelial cell gene expression of CCL5, TLR4, TNF, ZFP36, EDN1 and ITLN1 1 hour after infection with S. epidermidis." (PMID 28542390, 2017). "Soon after infection (8 hpi), the mRNA levels of the proinflammatory cytokines TNF-α and IL-1β were significantly elevated in the blood of WT and TLR4−/− mice." (PMID 28536433, 2017). "In the present study, we showed that TLR4, RIG-I and MDA5 were expressed in the liver in both Z8S2 and Z8R2 Pekin ducklings after infection, indicating the ducklings were able to mount a normal, early immune defense." (PMID 28674528, 2017). "Blocking of TLR4 signaling significantly reduced both EBOV-induced T cell death and infection of monocytes." (PMID 28542576, 2017).